HOXA1 (homeobox A1)
Diseases named in the same sentence as HOXA1 in open-access papers (continued):
Sharing a sentence is not in itself a finding about the gene and the disease.
breast carcinoma (continued). "HOXA1 is a well-reported oncogene that is upregulated in human malignancies including HNSCC, breast cancer, and non-small-cell lung cancer." (PMID 36119466, 2022). "Overlap analysis also showed that especially genes oppositely correlated to HOXA1 mRNA expression but positively to ER expression are enriched, suggesting that HOXA1 could be involved in the downregulation of these genes and thereby act as an ERα repressor in breast cancer." (PMID 34490074, 2021). "This supports a functional interaction between HOXA1 and ER in breast cancer, ESR1 expression improving the HOXA1+ condition, while HOXA1 expression worsening the survival probability of ER+ patients." (PMID 34490074, 2021). "HOXA1, a member of the HOX gene family, is an epithelial oncogene in breast cancer development and can induce the aggressive transformation of epithelial cells in vivo." (PMID 32497022, 2020). "This provides a new method for endocrine therapy of breast cancer patients; that is, ACK1 inhibitor AIM-100 or dasatinib inhibits ACK1 signal to alleviate the upregulation of drug resistance by HOXA1 in breast cancer patients." (PMID 31772931, 2019). "Furthermore, Spearman correlation heatmap analysis revealed a strong positive correlation among the expressions of LincRNA H19, miR-675, MRP3, HOXA1, and MMP16 in breast cancer tissues." (PMID 39267845, 2024). "In addition to the findings on SNPs and LincRNA H19, this study also investigated the expression of MRP3, HOXA1, and MMP16 in breast cancer tissues." (PMID 39267845, 2024). "HOXA1-mediated upregulation of PRLR (prolactin receptors) and their subsequent signal transduction is another important mechanism demonstrated in the oncogenic transformation of mammary carcinoma cells." (PMID 34617205, 2022). "HOXA1 is not the only homeodomain protein that functionally interacts with ERα and is correlated with poor prognosis of breast cancer." (PMID 34490074, 2021). "HOXA1 is not expressed in the normal adult mammary gland but has been shown to be upregulated in some breast cancer tissues." (PMID 34490074, 2021). "Together, our findings suggest that HOXA1 and its neighboring lncRNA, HOTAIRM1, might serve as potential therapeutic targets for ER+ breast cancer patients who have acquired tamoxifen resistance." (PMID 32284737, 2020). "HOXA1, a transcription factor of the HOX protein family, is overexpressed in many tumor cells and is involved in tumorigenesis and the development of several cancers including breast cancer." (PMID 32497022, 2020). "Knockdown of HOTAIRM1 or HOXA1 could re-sensitize TAMR cells to tamoxifen treatment, suggesting that the HOTAIRM1/HOXA1 axis contributes to tamoxifen resistance in breast cancer." (PMID 32284737, 2020). "Previous studies revealed that mTOR, HOXA1, and IGFBP1 were targeted by miR-99a in breast cancer; FGFR3 was targeted by miR-99a in bladder cancer; in the present study, we identified FGFR3 as a direct target of miR-99a in breast cancer for the first time." (PMID 32038996, 2019). "HOXA1, one of the HOXA gene cluster members, has been found to be up-regulated in human malignancies, such as non-small cell lung cancer, oral squamous cell carcinoma, uterine leiomyosarcoma and breast cancer, and function as an oncogene." (PMID 30376874, 2018). "In the human mammary gland, the expression of HOXA1 is very low or absent during normal growth and differentiation, but several studies have revealed its up-regulation in mammary carcinomas." (PMID 26417931, 2015). "While Hoxa1 is not expressed in the adult mammary gland, several studies revealed that it can be upregulated in mammary carcinomas." (PMID 21957483, 2011). "In this study, the expression levels of LincRNA H19, miR-675, MRP3, HOXA1, and MMP16 were consistently higher in 581 breast cancer tissues compared to adjacent non-tumor tissues." (PMID 39267845, 2024).
breast carcinoma (continued). "Meanwhile, HOXA1 hypermethylation is related to the absence of HER2 neu expression and proliferation of breast cancer cells (P < 0.05)." (PMID 33763449, 2020).
lung carcinoma (21 papers, 2007 to 2025). "Conversely, it functions as an oncogene in pancreatic ductal adenocarcinoma, breast cancer, and lung cancer by directly regulating HOXA1 expression." (PMID 39553554, 2024). "By directly regulating the expression of HOXA1, HOTAIRM1 has been implicated in the promotion of tumor malignancy in lung cancer and glioma." (PMID 39553554, 2024). "For instance, miR-577 directly targets HOXA1, and the functional effect of miR-577 on lung cancer cells is contingent upon HOXA1." (PMID 38311789, 2024). "The results of the rescue assays indicated that LINC00958 promotes lung cancer progression by regulating the transcriptional activity of HOXA1." (PMID 35223488, 2022). "HOTAIRM1 was shown to promote tumor malignancy by directly regulating HOXA1 expression in lung cancer and glioma." (PMID 31477638, 2019). "Correlation analysis showed that HOXA1 levels were negatively correlated with the proportion of MDSCs and the Arg1 levels in the peripheral blood of patients with lung cancer." (PMID 29662483, 2018). "The expression level of HOXA1 was detected in isolated MDSCs from tumor tissues of patients with lung cancer and in induced MDSCs from PBMCs of healthy donors." (PMID 29662483, 2018). "Notably, HOXA1 has shown highly significant hypermethylation in lung cancer, which holds promise as a potential marker for early detection of LUAD." (PMID 38311789, 2024). "In conclusion, HOXA1 plays a significant role in the regulation of the development and progression of major cancers that have a substantial impact on human survival, including lung cancer, BC,CRC, GC, and liver cancer." (PMID 38311789, 2024). "The transcription factor HOXA1, which regulates genes related to cell proliferation, differentiation, and immune response, has been reported to contribute to the pathogenesis of several malignancies, including lung cancer." (PMID 35223488, 2022). "WNT, TGF-beta and FGF pathways may synergistically affect HOXA1 expression, and WNT7A directly maintains expression of HOXA1, making for lung cancer recurrence." (PMID 33763449, 2020). "Additionally, the expression of HOTAIRM1 and its target gene HOXA1 were negatively associated with the ratio of MDSCs and ARG-1 levels in PBMCs of patients with lung cancer." (PMID 32083005, 2020). "Moreover, a positive association has been observed between the expression of HOTAIRM1 and HOXA1 in patients with lung cancer." (PMID 31404149, 2019). "Detection of HOXA1 levels in peripheral blood confirmed that HOXA1 expression levels were decreased in lung cancer patients compared with healthy controls, and further study indicated that the HOXA1 level was highest in lung ADC compared with small cell lung cancer and squamous cell lung carcinoma." (PMID 29662483, 2018). "Moreover, the HOXA1 level in the peripheral blood of lung cancer patients was positively correlated with the expression level of HOTAIRM1." (PMID 29662483, 2018). "In addition, the expression level of HOXA1 was increased in the peripheral blood of lung cancer patients postoperation." (PMID 29662483, 2018). "Taken together, this study illustrates that HOTAIRM1/HOXA1 downregulates the immunosuppressive function of MDSCs and may be a potential therapeutic target in lung cancer." (PMID 29662483, 2018). "Interestingly, ectopic expression of miR-30e resulted reduced cell proliferation andmigration, withinduced apoptosisin lung cancer cells by suppressing the key target HOXA1." (PMID 27992364, 2017). "Although we confirmed that miR-30e could inhibit lung cancer by targeting HOXA1, there might be other miR-30etargets, which could also affect tumor growth in lung cancer." (PMID 27992364, 2017). "For example, HOXA1 stimulates oncogenesis through the MAPKsignaling pathway and the transcription factors STAT3 and STAT5B in mammary epithelial cells.Also, CpG islands of HOXA1 are significantly hypermethylated in lung cancer, breastcancer and gastric carcinoma." (PMID 23142963, 2013).
lung carcinoma (continued). "Notably, HOXA1 expression is consistently upregulated in lung cancer, GC, and liver cancer." (PMID 38311789, 2024). "In lung cancer cells, HOTAIR has been shown to reduce the methylation of homeobox A1 (HOXA1), a protein involved in cell proliferation and apoptosis, which is often associated with poor clinical outcomes when overexpressed." (PMID 38256203, 2024). "Evidence has demonstrated that homeobox (HOX) A1 (HOXA1) and HOXA11 play oncogenic roles in lung cancer, and they are the putative target genes of miR-181c-3p, as same as ZIC2, as analyzed by the bioinformatics analysis using the starBase database." (PMID 34232917, 2021). "Therefore, HOTAIRM1/HOXA1 might be a potential therapeutic target for lung cancer." (PMID 32083005, 2020). "The ability of the top four candidates, CDKN2A EX2, CDX2, HOXA1 and OPCML (all p < 1 × 10-9), to individually identify lung cancer samples was next evaluated." (PMID 17967182, 2007). "This was in contrast to their target mRNA expressions (TXNRD1 and HOXA1), thus providing a molecular link between air pollution and non-smoker lung cancer." (PMID 41329722, 2025). "HOXA1 and HOXA11 have been identified to play oncogenic roles in lung cancer." (PMID 34232917, 2021). "Similar to HOTAIRM1, HOXA1 expression levels were negatively correlated with the proportion of MDSCs and Arg1 levels and positively correlated with the number of Th1/CTL cells in the peripheral blood of patients with lung cancer." (PMID 29662483, 2018).
cervical cancer (13 papers, 2015 to 2025). A primary or metastatic malignant neoplasm involving the cervix. "HOX genes have been found to be associated with oncogenesis, and HOXA1 is actively involved in several malignancies, such as endometrial cancer, cervical cancer, and non-small cell lung cancer." (PMID 34589524, 2021). "Allicin inhibits biological activities of cervical cancer cells through down‐regulating circEIF4G2/HOXA1/AKT/mTOR." (PMID 38628206, 2024). "Allicin depresses biological activities of cervical cancer cells through down‐regulating circEIF4G2/HOXA1/AKT/mTOR." (PMID 38628206, 2024). "We identified three differentially expressed HOXA members in cervical cancer (upregulated HOXA1 and downregulated HOXA10 and HOXA11)." (PMID 34606634, 2021). "Our results showed that among three differentially expressed HOXA genes (HOXA1, HOXA10, and HOXA11), HOXA1 was the only prognostic gene in cervical cancer." (PMID 34606634, 2021). "Various circRNAs (such as circSLC26A4, circ-ATP8A2) promoted the oncogenesis of cervical cancer by increasing the downstream mRNAs, including HOXA1 and EGFR via sponging miRNAs." (PMID 34596142, 2021). "Firstly, patients with cervical cancer were classified into two different group based on the cutoff value of HOXA1, HOXA10, and HOXA11 expression from ROC." (PMID 34606634, 2021). "In particular, the upregulation of the HOXA1, HOXA5, and HOXA6 genes were found to be significantly associated with unfavorable overall survival in patients with cervical cancer." (PMID 29137433, 2017). "In this study, we showed that the increased mRNA expression of four HOX genes—HOXA1, HOXA5, HOXA6, and HOXC11—is independently associated with mortality in cervical cancer based on data from TCGA." (PMID 29137433, 2017). "The three members of miR-99 family show relevance in cervical carcinoma since it has been shown a down-regulation of mRNA and protein of Homeobox A1 (HOXA1) and mTOR via 3′UTR in HaCaT cells." (PMID 28216603, 2017). "In cervical cancer the expression of miR-99b and miR-125a are opposite, suggesting a specific selection of miR-125a over miR-99b, resulting in HOXA1 and mTOR overexpression." (PMID 26057746, 2015). "The expression of miR-99a and miR-125b-2 is downregulated in cervical cancer, causing TRIB2, HOXA1, and mTOR overexpression probably by the combination of both miRNAs’ loss." (PMID 26057746, 2015). "Eventually, the HOXA1 could be served as an independent prognostic biomarker for poor outcome of cervical cancer." (PMID 34606634, 2021). "Considering favorable efficacy in immune checkpoint inhibitors (especially PD‐1/PD‐L1 inhibitors) achieved in treating cervical cancer, our study also assessed the expression status of CTLA4, PD‐1, and PD‐L1 in cervical cancer patients grouped by different expression of HOXA1, HOXA10, and HOXA11." (PMID 34606634, 2021). "The HOXA1 gene could serve as an independent prognostic factor for poor OS in patients with cervical cancer." (PMID 34606634, 2021). "Downregulation of HOXA1 was related to a poor outcome for cervical cancer patient." (PMID 34606634, 2021). "A recent study also reported that LINC00152 could modulate the proliferation of cervical cancer (CC) cells through elevating HOXA1 expression level via sponging miR-216b-5p." (PMID 31920462, 2020). "In conclusion, in this study, we showed that the upregulation of the expression of the HOXA1, HOXA5, and HOXA6 genes are significantly associated with unfavorable overall survival as well as increased mortality in a large cohort of cervical cancer cases from TCGA database." (PMID 29137433, 2017).
cervical cancer (continued). "In addition, HOXA1 expression levels in squamous cell lung-and cervical cancer tissue samples are significantly elevated compared with adjacent normal tissue specimens." (PMID 27992364, 2017). "After normalization of the other clinical features (including TNM stage), only HOXA1 and HOXA3 expression was still associated with poor OS of cervical cancer, indicative of the fact that these two HOXA members could serve as independent predictive biomarkers of cervical cancer." (PMID 34606634, 2021). "This research highlights BIRC5, HOXA1, and RARB as significant therapeutic targets in cervical cancer due to their critical involvement in its development." (PMID 40564176, 2025). "Through this analysis, certain genes, including BIRC5 (survivin), HOXA1, and RARB, were identified as highly relevant in cervical cancer due to their topological properties and high scores in databases like Genecards." (PMID 40564176, 2025). "The expression profile of HOXA family was presented by pheatmap of R software, the result showing significant differences in HOXA1, HOXA10, and HOXA11 expression between cervical cancer and normal controls." (PMID 34606634, 2021). "Firstly, we compared the expression of HOXA members in cervical cancer than normal controls, and results showed only three HOXA members with statistical significance (HOXA1, HOXA10, and HOXA11)." (PMID 34606634, 2021). "The expression of HOXA1 was significantly upregulated in cervical cancer compared to normal control, whereas HOXA10 and HOXA11 were downregulated in cervical cancer." (PMID 34606634, 2021). "Our results showed that the HOXA1 gene was upregulated, while the HOXA10 and HOXA11 were downregulated in cervical cancer." (PMID 34606634, 2021). "In summary, this study represented the expression status of HOXA members in cervical cancer and identified three differentially expressed HOXA genes (HOXA1, HOXA10, and HOXA11) with great discriminative ability in cervical cancer." (PMID 34606634, 2021). "miR-10b-5p has been shown decreased in cervical cancer as well as in pre-malignant steps and its overexpression reduces proliferation and invasion via 3′UTR down-regulation of Homeobox A1 (HOXA1)." (PMID 28216603, 2017). "Upregulated HOXA1, HOXA5, and HOXA6 expression are significantly correlated with unfavorable overall survival and increased mortality in cervical cancer patients." (PMID 29137433, 2017). "Similarly, miR-10b-5p, often downregulated in cervical cancer tissues, inhibits cell proliferation, migration, and invasion by targeting insulin-like growth factor-1 receptor (IGF-1R) and Homeobox A1 (HOXA1)." (PMID 39796267, 2025). "Our results demonstrated that the expression of HOXA1 was upregulated in cervical cancer (p value for HOXA1 = 0.0128), while HOXA10 and HOXA11 expression was downregulated in cervical cancer compared with the normal control (p value for HOXA10 = 0.0123, p value for HOXA11 = 8.045E‐5)." (PMID 34606634, 2021). "In another study, the miRNAs, miR-203 and miR-30b and the target genes BIRC5, HOXA1, and RARB were suggested to be critical players in the pathogenesis of cervical cancer, as revealed by the systematic analysis of dysregulated miRNAs and their targets in cervical cancer." (PMID 30020984, 2018). "Pearson's correlation results showed that almost all assessed cg sites of HOXA1, HOXA10, and HOXA11 exhibited a negative correlation with expression in cervical cancer." (PMID 34606634, 2021).